CD274 (CD274 molecule)
Diseases named in the same sentence as CD274 in open-access papers (continued):
Sharing a sentence is not in itself a finding about the gene and the disease.
breast cancer (continued). "The MYC pathway, PD-L1 (CD274) and CD47 were elevated in TNBC, particularly in PTEN-low/miRNA-low TNBCs (group “a”), relative to HER2+ or ER+ breast cancer in most cohorts." (PMID 31836816, 2019). "The qRT-PCR results showed that CD274 and IL8 were upregulated in the basal-like breast cancer cell lines BT549 and MDA-MB-231 (p < 0.01)." (PMID 31293831, 2019). "Third, IO targets CD274 and IL8 which were confirmed to be more suitable for the treatment of basal-like breast cancer." (PMID 31293831, 2019). "This is the first large cohort analysis of PD-L1 protein, in situ mRNA expression and CD274 gene amplification in TNBC breast cancer." (PMID 27390646, 2016). "Upregulation of the PD-L1 (CD274) immune checkpoint ligand on the tumor surface facilitates tumor immune escape and limits the application of immunotherapy in various cancers, including breast cancer." (PMID 37340461, 2023). "Moreover, the expression of LAG3, CTLA-4, PD-L1, CD274, TIGIT, HAVCR2 and PDCD1LG2 was upregulated in the TFRC high-expression group compared with the TFRC low-expression group in breast cancer." (PMID 35847985, 2022). "Additionally, FOXP3 has a significant positive correlation with PDCD1, CD274, CTLA4 and TMB in breast cancer, and FOXP3 expression showed a statistically significant correlation with infiltration of immune cells." (PMID 35614183, 2022). "Additionally, we found that FOXP3 had a significant positive correlation with PDCD1, CD274, CTLA4 and TMB in breast cancer." (PMID 35614183, 2022). "Significantly, we found that in tumor-infiltrating macrophages isolated from human endometrial and breast cancers, the IRE1α gene signature is a better predictor of CD274 (PD-L1) transcription than the PERK gene signature, confirming the conclusion reached in mouse macrophages." (PMID 32520957, 2020). "In addition, SLC31A1 was positively related to the expressions of immune checkpoints CD274 and CTLA4, suggesting that targeting SLC31A1 might be a potential way to improve immunotherapy efficacy in breast cancer." (PMID 37884650, 2023). "In the present study, MYL5 expression negatively correlated with the markers of T cells exhaustion, such as PDCD1 (PD-1), CD274 (PD-L1), and CTLA4 (cytotoxic T-lymphocyte antigen 4), which indicated that MYL5 could play a positive role in prolonging survival prognosis for breast cancer patients." (PMID 36846347, 2023). "We demonstrated the detection rate of SV in CD274 UTR region in a large-scale retrospective Chinese cohort for the first time, and found that the incidence ratio of SV in CD274 UTR region was significantly higher than TCGA cohort in liver and breast cancer but consistent in pan-cancer." (PMID 36717553, 2023). "We cannot rule out a similar role for CD274 in our breast cancer model." (PMID 36009475, 2022). "Furthermore, we further analysis the correlation of risk score and immune checkpoint in breast cancer and demonstrated that most of key checkpoint were significantly differentially expressed between the two groups in breast cancer patients, including CD44, TIGIT, CTLA4, CD274, CD86 and CD80." (PMID 35052427, 2021). "The results showed that in breast cancer, GPS1 expression was positively correlated with LAG3, PVRL2, and LGALS9, and negatively correlated with CD274 and HAVCR2, but not with CTLA4 and PDCD1." (PMID 38289496, 2024). "In addition, the amount of CD274 showed no obvious increase in some cancers when compared with counterparts from healthy donors, especially those in PDAC, breast cancer, and ovarian cancer, indicating VSIG4+ TAMs is an unignorable subpopulation in the TME." (PMID 39920772, 2025). "By mass spectrometry analysis performed in a breast cancer stem cell model (human mammary epithelial HMLER CD24low/CD44high), salinomycin, a ferroptosis inducer, was capable of inducing protein upregulation of CD274 and TNFAIP3 without any modulation of PDCD1." (PMID 38201582, 2023).
breast cancer (continued). "The protein expression levels of the two immune checkpoint molecules, CD200R and CD274, were measured as mean fluorescence intensity (MFI) in non-hematopoietic cells, identified by the expression of cytokeratin 18 and CD326 (EpCAM) and dim/negative expression of CD45, from breast cancer biopsies." (PMID 39858472, 2025).
non-small cell lung carcinoma (2,356 papers, 2014 to 2026). A group of at least three distinct histological types of lung cancer, including non-small cell squamous cell carcinoma, adenocarcinoma, and large cell carcinoma. "By developing a NRF2 gene signature, we found that it more effectively predicts anti-PD1 therapy responses than CD274 alone in non-small cell lung cancer." (PMID 38241355, 2024). "Promoter methylation inversely correlates with CD274 levels across several cancers in gastric cancer, diffuse low-grade glioma, and non-small cell lung cancer, hypermethylation suppresses CD274 transcription, whereas hypomethylation enhances expression and immunosuppressive activity." (PMID 41409271, 2025). "Our analysis was consistent with similar analysis completed in human non-small cell lung cancer in which PLAU, PLAUR, IL1R2, CD274, OSM, and CXCL8 were reported to be significantly enriched in TANs relative to circulating neutrophils." (PMID 39932553, 2025). "Statistical analysis revealed that in non-small cell lung cancer (NSCLC) and colon cancer, ALDH1A1 and ZBTB7B were positively correlated with CD274 mRNA expression." (PMID 39107297, 2024). "The CD274 and PDCD1 immune checkpoint interaction could accelerate cancer progression in the colorectal cancer microenvironment and elderly non-small cell lung cancer patients." (PMID 37608927, 2023). "The underlying reason of the increased expression of CD274 and PDCD1LG2 in ATC with CDKN2A loss is not unveiled in this study, but their potential relationship in non-small cell lung cancer were previously reported." (PMID 31235699, 2019).
gastric cancer (1,280 papers, 2013 to 2026). A primary or metastatic malignant neoplasm involving the stomach. "In gastric cancer, there is a frequent somatic mutation in CD274 3′ UTR leads to protein over-expression by disrupting miR-570 binding." (PMID 26062441, 2015). "Mutation of CD274 leading to its overexpression have been associated with gastric carcinoma." (PMID 27829003, 2016). "Intriguingly, data from the TGCA gastric cancer dataset show that EBV-positive gastric cancer frequently exhibits amplification at 9p24.1, a locus containing CD274 and PDCD1LG2 (encoding PD-L1 and PD-L2), which is associated with a more immune-active profile." (PMID 40831929, 2025). "We additionally validated the positive correlation between PRDM1 and CD274 (programmed death ligand 1) in stomach cancer in the TCGA dataset (Figure A15)." (PMID 38540967, 2024). "Some research studies demonstrated that the CD274 high expression level was associated with a significantly better patient outcome, and PD-L1 mRNA levels were upregulated in gastric cancer, which are the same as our study." (PMID 32963532, 2020). "CD274 and PDCD1LG2 encode PD-L1 and PD-L2, respectively, which suggests a potential role of PD-1/PD-L1 pathway inhibitors in the treatment of gastric cancer." (PMID 28434400, 2017). "The authors identified distinct mutations and epigenetic profiles (recurrent PIK3CA mutations, high DNA hypermethylation levels and amplification of JAK2, CD274 and PDCD1LG2) in EBV-associated gastric cancer cases." (PMID 28454117, 2017). "The TCGA study also revealed that the amplification of CD274 and PDCD1LG2 (also encoding PD-L1 and PD-L2) was enhanced in the EBV-positive gastric cancer subgroup." (PMID 27012666, 2016). "Amplification of CD274 has been observed in the setting of EBV-positive gastric cancer and in samples of Hodgkin’s lymphoma from patients who have had a clinical response to PD-1 inhibition." (PMID 27390646, 2016). "In summary, elevated IL-10 and TGF-β1 levels in gastric cancer synergistically enhance immune checkpoint gene expression, including CD274 and CTLA4, thereby strengthening the immunosuppressive microenvironment and informing immune therapy resistance mechanisms and combined targeted strategies." (PMID 41438510, 2025). "Furthermore, the results of PCR showed that the expressions of CD274 in stomach cancer cells (AGS, MKN-45, and MGC-803) and liver cancer cells (HUH-7, HepG2, and SMMC-7721) were significantly lower than that in their normal cells." (PMID 38166842, 2024). "CD274 is located on chromosome 9p24.1, where amplifications and translocations are linked to upregulated expression of PD-L1 in Hodgkin's lymphoma, small cell lung cancer (SCLC), NSCLC, lymphoma, Epstein-Barr virus (EBV)-positive gastric cancer, and oral squamous cell carcinoma (OSCC)." (PMID 34088360, 2021). "A number of T cell co-inhibitory molecules CTLA4, ICOS, CD274, PDCD1, and IDO were markedly downregulated by NPRL2 treatment which was in agreement with the data found in bioinformatics analysis in stomach cancer patients' samples." (PMID 39932765, 2025). "Post-translational modifications (PTMs) of NF-κB subunits—including phosphorylation of p65 at Ser536 and acetylation at Lys310—enhance its transcriptional activity on the CD274 (PD-L1) promoter in diverse cancers such as NSCLC and gastric carcinoma." (PMID 41035656, 2025). "It has been found that PD-1 ligand (PD-L1), also known as B7H1 or CD274, is overexpressed on CSCs from CRC, head and neck squamous cell carcinoma, and gastric cancer, contributing to immune evasion of CSCs." (PMID 36910604, 2023). "In gastric cancer (GC), CXCL8 secreted by macrophages contributes to the immunosuppressive ecosystem by inducing CD274 macrophages." (PMID 37898619, 2023). "In gastric cancer, depletion of USP7 by p5091 decreased PD-L1 (Programmed Cell Death 1 Ligand 1, also known as CD274) expression and sensitized gastric cancer cells to T cell killing." (PMID 35307036, 2022).
gastric cancer (continued). "The immune checkpoint analysis indicated that gastric cancer patients with upregulated GGT5 expression showed a higher TIDE score and expression of CD274, CTLA4, HAVCR2, LAG3, PDCD1, PDCD1LG2, and TIGIT than patients in the GGT5-low expression group." (PMID 35368661, 2022). "Within the EBV subtype of gastric cancer, PD-L1 overexpression was shown to be triggered by two mechanisms: focal amplification of CD274 (PD-L1) and IFN-γ-mediated signaling via activation of IRF3 to increase PD-L1 expression." (PMID 34680363, 2021). "It should be noted that PLGRKT is located alongside JAK2, CD274 (PD-L1) and PDCD1LG2 (PD-L2) within the 9p24.1 locus that is commonly amplified in EBV-positive gastric cancers." (PMID 25613731, 2015). "Interestingly, the immune checkpoint genes CD274, CTLA4, CD276, and CD200 are upregulated by Notch3 in gastric cancer, leading to impaired immune responses." (PMID 39766289, 2024). "The FDA-approved PD-L1 IHC results with 22C3 pharmDx (gastric cancer) and SP142 (urothelial carcinoma) were compared with CD274 mRNA expression levels via qRT-PCR using the same formalin-fixed, paraffin-embedded tissue blocks from 59 gastric cancer and 41 urothelial carcinoma samples." (PMID 35574404, 2022). "We further demonstrated that SCRS data amplified by either MDA or MALBAC from a gastric cancer cell line could accurately detect gastric cancer CNVs with comparable sensitivity and specificity, including amplifications of 12p11.22 (KRAS) and 9p24.1 (JAK2, CD274, and PDCD1LG2)." (PMID 26251698, 2015).
colorectal cancer (1,023 papers, 2013 to 2026). A primary or metastatic malignant neoplasm that affects the colon or rectum. "Expression of IL10 and CD274 (also known as programmed death ligand 1) was associated with tumors, such as in the clinical manifestation of laryngeal squamous cell carcinoma and colorectal cancer-derived liver metastases." (PMID 38792803, 2024). "Several studies have reported that high levels of CD274 expression on monocytes are associated with poor prognosis in patients with colorectal cancer." (PMID 37370832, 2023). "In this study, we found that tumor CD274 expression level was inversely associated with the amount of Fusobacterium nucleatum in colorectal cancer tissue." (PMID 37538192, 2023). "Our study also showed that tumor CD274 overexpression was significantly associated with non‐MSI‐high colorectal cancer." (PMID 37538192, 2023). "In conclusion, we found that tumor CD274 expression level was inversely associated with the amount of F. nucleatum in colorectal cancer tissue." (PMID 37538192, 2023). "Tumor CD274 expression level was inversely associated with the amount of F. nucleatum in colorectal cancer tissue." (PMID 37538192, 2023). "Tumor CD274 expression level was inversely associated with the amount of F. nucleatum in colorectal cancer tissue (P = 0.0077)." (PMID 37538192, 2023). "Recently, tumor CD274 (PD-L1) expression is inversely associated with FOXP3+ cell density in colorectal cancer tissues and FOXP3 is expressed significantly higher in cytolytic-high colorectal tumors." (PMID 34768829, 2021). "Based on these findings, we hypothesised that tumor CD274 overexpression might be inversely associated with abundance of F. nucleatum in colorectal cancer." (PMID 37538192, 2023). "Tumor CD274 expression level was inversely associated with the amount of F. nucleatum in colorectal cancer tissue, suggesting that different immunosuppressive mechanisms (i.e. PDCD1 immune checkpoint activation and tumor F. nucleatum enrichment) tend to be used by different tumor subgroups." (PMID 37538192, 2023). "Tumor CD274 overexpression has been inversely associated with FOXP3+ regulatory T‐cell (Treg) density in colorectal carcinoma, suggesting that tumor CD274 expression and Treg infiltrates might be mutually exclusive immunoevasion mechanisms." (PMID 37538192, 2023). "We hypothesised that tumor CD274 overexpression might be inversely associated with abundance of F. nucleatum in colorectal carcinoma." (PMID 37538192, 2023). "BRAF mutation-positive colorectal cancers have also been shown to have increased PD-L1 expression, suggesting that the MAPK pathway is involved in the regulation of CD274 expression in the intestinal epithelium." (PMID 38920700, 2024). "Comprehensive bioinformatics analysis revealed a significant increase in PDIA3 expression in colorectal cancer, associated with STAT3, CD274, and markers of monocytic/macrophage lineage." (PMID 38761176, 2024). "First, we integrated clinical, pathological and tumor molecular data and then rigorously investigated the relationship between CD274 expression level and F. nucleatum in colorectal cancer tissue while adjusting for potential confounders, including MSI status." (PMID 37538192, 2023). "The expression of CD274 (also known as PD-L1) on monocytes has been studied concerning prognosis in patients with colorectal cancer." (PMID 37370832, 2023). "Antibodies targeting PD-1 (programmed cell death 1, also known as PDCD1) and PD-L1 (PDCD1 ligand 1, also known as B7H1 and CD274) are promising strategies in many cancer types, including colorectal cancer." (PMID 37875976, 2023). "B7-H1, PD-L1, or CD274 are upregulated in colorectal carcinoma and have been linked to cell differentiation and tumor-node-metastasis placement." (PMID 36551617, 2022).
colorectal cancer (continued). "Emerging evidence suggests that the stratification of colorectal cancer microenvironment based on tumor-infiltrating lymphocytes (TILs) and CD274 expression is a biomarker and strong predictor of disease recurrence and survival in patients with CRC." (PMID 33425745, 2020). "Interestingly, high IFNγ expression correlated with high STAT1 or CD274 expression in colorectal cancer, but high CBX3 expression was significantly associated with low expression levels of STAT1 or CD274." (PMID 38684864, 2024). "Moreover, analyses predicated on TIMER2.0 insinuated a positive correlation between CD274 and the monocytes/macrophages axis, alluding to their potential complicity in the colorectal cancer spectrum." (PMID 38761176, 2024). "Tumor CD274 expression level was inversely associated with the amount of F. nucleatum in colorectal cancer tissue with nonsignificant but suggestive evidence at the stringent α level of 0.005 (P = 0.0077)." (PMID 37538192, 2023). "In Affymetrix primeview human GeneChip array, we found six upregulated genes (STAT1, ATF2, TNFRSF10B, TGFBR2, BAX, and SQSTM1) and two downregulated genes (SLC4A7 and CD274) related to apoptosis and proliferation of colorectal cancer cells after hsa_circ_0064559 knockdown." (PMID 37280630, 2023). "A subset of colorectal carcinomas have been shown to overexpress CD274 (PD‐L1), which may contribute to tumor immunoevasion." (PMID 37538192, 2023). "In this study, we found that tumor CD274 (PD‐L1) expression was inversely associated with tissue F. nucleatum abundance in colorectal carcinoma, independent of other clinical and molecular features including MSI status." (PMID 37538192, 2023). "However, the clinical significance of CD274 in colorectal cancer were still elusive." (PMID 30353144, 2018). "Specifically, in MSI colorectal cancers, immune ESTIMATE, HAVCR2 (TIM-3), CD274 (PD-L1), LAG3 (LAG-3), and PDCD1 (PD-1) each showed significant inverse correlations with GALNT7 expression across the three cohorts." (PMID 40824763, 2025). "A variety of malignancies, particularly colorectal cancer with significant microsatellite instability, have shown improved clinical outcomes when treated with inhibitors targeting CD274 (PD-L1) or PDCD1 (PD-1) proteins." (PMID 39115621, 2024). "In a study utilizing colon inflammation and colorectal cancer models, HP1γ was found to reside on STAT1 and CD274 promoters to mediate their transcriptional repression, which is alleviated upon IFNγ signaling." (PMID 39519018, 2024). "In colorectal cancer, mregDCs expressed LGALS9 and PD‐L1 (CD274) in tumour tissues from patients who received presurgical chemotherapy or not, while the production of chemokines recruiting Tregs, such as CCL19 and CCL10, was reduced in the treated patients." (PMID 36808888, 2023). "In the present study, we used multiplex immunohistochemistry combined with digital image analysis and quantitative density and spatial analysis to comprehensively characterise the expression of PD-L1 (CD274) and PD-1 (PDCD1) immune checkpoints in the colorectal cancer microenvironment." (PMID 37002343, 2023). "Furthermore, a positive correlation was observed between the expression of CDKN2A and various immune checkpoint genes in colorectal cancer, namely PDCD1, CTLA-4, and CD274." (PMID 37950153, 2023). "Based on these data and the correlations with cytokine levels, it can be concluded that CD25, CD80, CD86, CD274 and CD279 glycoproteins combined with specific plasma levels of IL-1β, IL-2, IL-15 and TGFβ could represent potential biomarkers for colorectal cancer." (PMID 39456247, 2024). "The CD274 (PD-L1)/PDCD1 (PD-1) immune checkpoint interaction may promote cancer progression, but the expression patterns and prognostic significance of PD-L1 and PD-1 in the colorectal cancer microenvironment are inadequately characterised." (PMID 37002343, 2023).